SLC22A4 (solute carrier family 22 member 4)
Description:
Transporter that mediates the transport of endogenous and microbial zwitterions and organic cations. Functions as a Na(+)-dependent and pH-dependent high affinity microbial symporter of potent food-derived antioxidant ergothioeine. Transports one sodium ion with one ergothioeine molecule (By similarity). Involved in the absorption of ergothioneine from the luminal/apical side of the small intestine and renal tubular cells, and into non-parenchymal liver cells, thereby contributing to maintain steady-state ergothioneine level in the body. Also mediates the bidirectional transport of acetycholine, although the exact transport mechanism has not been fully identified yet. Most likely exports anti-inflammatory acetylcholine in non-neuronal tissues, thereby contributing to the non-neuronal cholinergic system. Displays a general physiological role linked to better survival by controlling inflammation and oxidative stress, which may be related to ergothioneine and acetycholine transports. May also function as a low-affinity Na(+)-dependent transporter of L-carnitine through the mitochondrial membrane, thereby maintaining intracellular carnitine homeostasis. May contribute to regulate the transport of cationic compounds in testis across the blood-testis-barrier.
Synonyms: ETTh; OCTN1; MGC34546; DFNB60
Tractability: Small molecule: it belongs to a druggable protein family. Antibody: UniProt places it where antibodies can reach, with high confidence; its Gene Ontology location is reachable by antibodies, with high confidence; UniProt predicts a signal peptide or a membrane-spanning region.
Target class: SLC superfamily of solute carriers; Electrochemical transporter; SLC22 family of organic cation and anion transporters; Transporter
Gene: Protein-coding gene on chromosome 5 (132,293,769 to 132,344,206, forward strand). Ensembl gene ENSG00000197208.
Subcellular location: Apical cell membrane; Basal cell membrane; Mitochondrion membrane
Subcellular location (Human Protein Atlas): Mitochondria
Pathways (Reactome):
Metabolism: Choline catabolism
Transport of small molecules: SLC-mediated transport of organic cations
Gene Ontology:
Molecular function: acetylcholine transmembrane transporter activity; amino acid transmembrane transporter activity; amino-acid betaine transmembrane transporter activity; carnitine transmembrane transporter activity; PDZ domain binding; protein binding; quaternary ammonium group transmembrane transporter activity; secondary active transmembrane transporter activity; ATP binding; transmembrane transporter activity
Biological process: amino acid import across plasma membrane; carnitine transport; quaternary ammonium group transport; amine transport; choline catabolic process; acetylcholine uptake; carnitine transmembrane transport; lactation; liver regeneration; neurotransmitter transport; response to exogenous dsRNA; response to lipopolysaccharide; response to vitamin D; sodium-independent organic anion transport; sulfur amino acid transport; transmembrane transport
Cellular component: apical plasma membrane; basal plasma membrane; mitochondrial membrane; mitochondrion; mitochondrial outer membrane; plasma membrane; membrane; neuronal cell body
Genetic constraint (gnomAD): Loss-of-function variants: 29 observed, 40.26 expected, observed/expected ratio (o/e) 0.72, 90% interval 0.54 to 0.98. The upper end of that interval is the gene's LOEUF score, 0.98, which puts it in group 4 of 6, group 1 being the genes least tolerant of losing a copy. Missense variants: 505 observed, 607.68 expected, observed/expected ratio (o/e) 0.83, 90% interval 0.77 to 0.89. Synonymous variants: 207 observed, 250.47 expected, observed/expected ratio (o/e) 0.83, 90% interval 0.74 to 0.93.
Gene-disease validity (ClinGen):
ClinGen rates the evidence that SLC22A4 causes each of these diseases.
hearing loss, autosomal recessive (autosomal recessive): Limited.
Homologues: Orthologues: chimpanzee SLC22A4 (99% identical), macaque SLC22A4 (98% identical), pig SLC22A4 (88% identical), rat Slc22a4 (86% identical), mouse Slc22a4 (85% identical), guinea pig SLC22A4 (83% identical), tropical clawed frog slc22a5 (70% identical), tropical clawed frog slc22a4 (65% identical), zebrafish slc22a4 (48% identical), Drosophila melanogaster Orct (33% identical), Drosophila melanogaster Orct2 (32% identical), zebrafish si:dkey-166k12.1 (30% identical), and 42 more. Paralogues in human: SLC22A5 (77% identical), SLC22A16 (33% identical), SLC22A2 (32% identical), SLC22A15 (32% identical), SLC22A1 (31% identical), SLC22A13 (29% identical), SLC22A8 (29% identical), SLC22A12 (28% identical), SLC22A7 (28% identical), SLC22A3 (28% identical), SLC22A6 (27% identical), SLC22A11 (26% identical), and 10 more.
Diseases named in the same sentence as SLC22A4 in open-access papers:
SLC22A4 is named in the same sentence as 82 diseases in open-access papers, as found by Europe PMC text mining. Sharing a sentence is not in itself a finding about the gene and the disease. The quoted sentences say what the papers report.
Crohn disease (26 papers, 2006 to 2025). A gastrointestinal disorder characterized by chronic inflammation involving all layers of the intestinal wall, noncaseating granulomas affecting the intestinal wall and regional lymph nodes, and transmural fibrosis. "Crohn’s disease is associated with the T alleles in SLC22A4 in contrast to our observation of reduced tooth loss with the TT constellation." (PMID 32964310, 2021). "Single nucleotide polymorphisms (SNPs) of Solute carrier family 22, member 4 (SLC22A4) have been shown to be associated with several autoimmune diseases, including Crohn’s disease (CD) and rheumatoid arthritis (RA)." (PMID 26329403, 2015). "Carnitine transporter mutations in Crohn's disease consists of missense mutation(s) in the gene coding plasma membrane transporter OCTN1 (SLC22A4) and/or mutation(s) in the promoter of the gene encoding OCTN2 (SLC22A5)." (PMID 20398344, 2010). "The gene SLC22A4 is contained within the larger IBD5 locus, which consists of a group of genes with polymorphisms linked to gastrointestinal disorders such as Crohn’s disease." (PMID 40694589, 2025). "SLC22A4 polymorphisms are associated with the incidence of inflammatory bowel disease (IBD), Crohn’s disease (CD) and ulcerative colitis (UC)." (PMID 38112574, 2023). "Functional gastrointestinal disorders (FGID) studies have shown that genes related to asthma, such as DENND1B, SMAD3, SLC22A4/5 (5q31/IBD5), and ORMDL3, have been co-associated with Crohn's disease and ulcerative colitis." (PMID 37656879, 2023). "Our analysis resulted in five candidate genes corresponding to two of the major IBD subtypes: UBE2L3 and SLC22A4 for Crohn’s Disease and TCF19, C6orf47 and SNAPC4 for Ulcerative Colitis." (PMID 34968289, 2020). "Carnitine’s role in the GI tract has recently been highlighted by several publications linking mutations in genes encoding carnitine transporters OCTN1 (SLC22A4) and OCTN2 (SLC22A5) with Crohn’s disease." (PMID 25757041, 2015). "Carnitine’s role in the GI tract has recently been highlighted by several publications linking mutations in genes encoding carnitine transporters OCTN1 (SLC22A4) and OCTN2 (SLC22A5) with Crohn’s disease (CD)." (PMID 23112839, 2012). "Carnitine’s role in the GI tract has recently been highlighted when several reports linked mutations in genes encoding carnitine transporters OCTN1 (SLC22A4) and OCTN2 (SLC22A5) with Crohn’s disease (CD)." (PMID 23112839, 2012). "Functional variants of SLC22A4 and SLC22A5 ion transporter genes that alter their transcription and transporter functions are associated with the Crohn's disease IBD5 locus." (PMID 19898610, 2009). "The chromosomal region 5q31 contains several genes involved in immune and inflammatory responses and the SLC22A4 and SLC22A5 genes were associated with two autoimmune diseases (rheumatoid arthritis and Crohn's disease)." (PMID 16796743, 2006). "Polymorphisms in the carnitine transporters, encoded by the SLC22A4 and SLC22A5 genes, have been involved in susceptibility to two other autoimmune diseases, rheumatoid arthritis and Crohn's disease." (PMID 16796743, 2006). "Recent reports performed associations of some polymorphisms within the SLC22A4 and SLC22A5 genes with two other autoimmune complex diseases (rheumatoid arthritis and Crohn's disease)." (PMID 16796743, 2006). "Moreover, an association with both asthma and Crohn’s disease was found for gene loci DENND1B, SMAD3 and SLC22A4/5 (5q31/IBD5), while the ORMDL3 gene variants present in Crohn’s disease and ulcerative colitis were also associated with childhood-onset asthma." (PMID 37835065, 2023). "At a false discovery rate (FDR) of 5%, we observed a significant enrichment of SLC22A4, SLC22A5, and P4HA2 genes for Crohn’s disease and inflammatory bowel disease (IBD)." (PMID 26053627, 2015).
rheumatoid arthritis (14 papers, 2006 to 2024). A chronic, systemic autoimmune disorder characterized by inflammation in the synovial membranes and articular surfaces. "Meanwhile, the genetic polymorphisms SLC22A4 rs2073838 and rs3792876 were reported to be significantly associated with rheumatoid arthritis (RA) in the Japanese population and Chinese population." (PMID 35962388, 2022). "The SLC22A4 gene was identified as a susceptibility gene for rheumatoid arthritis, and it was negatively regulated by RUNX1, a transcription factor which was also significantly associated with rheumatoid arthritis." (PMID 35154281, 2022). "Genetic polymorphisms have been found to affect SLC22A4 gene expression and to be associated with autoimmune diseases such as rheumatoid arthritis (RA),CD and type 1 diabetes (T1D)." (PMID 26329403, 2015). "Also, NF-kB overexpression is involved in the inflammatory response associated with rheumatoid arthritis through activation of the SLC22A4 promoter." (PMID 38112574, 2023). "The association of the intronic slc2F2 polymorphism in the SLC22A4 gene with rheumatoid arthritis (RA) was originally reported in a Japanese population." (PMID 16796743, 2006). "The overexpression of NF-κB can participate in the rheumatoid arthritis-related inflammatory response by activating the SLC22A4 promoter." (PMID 35962388, 2022). "Reduced RUNX1 binding caused by intronic SNPs has been proposed to cause aberrant regulation of PDCD1 (the programmed cell death 1 gene) in patients with systemic lupus erythematosus, and of SLC22A4 in patients with rheumatoid arthritis." (PMID 17786197, 2007). "Interestingly, several studies have suggested that RUNX1 regulates the expression of another transporter, SLC22A4, in rheumatoid arthritis." (PMID 29759484, 2018).
inflammatory bowel disease (11 papers, 2013 to 2024). A spectrum of small and large bowel inflammatory diseases of unknown etiology. "Also, the expression of other SLC family members were reported in response to nematode infection in both susceptible and resistant sheep and variants in the SLC22A4 gene have been associated to Inflammatory Bowel disease in humans." (PMID 29703268, 2018). "The promoter region of the SLC22A4 gene has been extensively studied due to its involvement in inflammatory bowel diseases (IBDs) and drug transport." (PMID 39201429, 2024).
asthma (7 papers, 2020 to 2024). "IBD and asthma also share susceptibility genes, including gene loci DENND1B, SMAD3, SLC22A4/5 (5q31/IBD5) and ORMDL3 gene variants." (PMID 37835065, 2023). "Expression levels of SLC22A4 (P = 0.0051, MA and <0.0001, SA) was lower in both mild-moderate and severe asthma subjects compared to controls." (PMID 35386986, 2021). "Expression levels of SLC22A4 (P = 0.0028) was decreased in severe asthma compared to mild-moderate asthma." (PMID 35386986, 2021). "Distinct genetic loci, including mothers against decapentaplegic homolog 3 (SMAD3), DENN domain containing 1B (DENND1B), and Solute carrier family 22, member 4/5 [SLC22A4/5 (5q31/IBD5)], are known to be associated with both CD and asthma." (PMID 32181078, 2020).
chronic myeloid leukemia (6 papers, 2017 to 2024). "In previous work, we identified SNP rs460089 located in the promotor of SLC22A4 gene encoding imatinib transporter OCTN1 as influential on response of patients with chronic myeloid leukemia treated with imatinib." (PMID 38129513, 2024). "Furthermore, LC-MS/MS and RNA-seq assays reveal that SOS1 negatively regulates the expression of SLC22A4, a member of the carnitine/organic cation transporter family, which mediates the active uptake of imatinib into chronic myeloid leukemia cells." (PMID 34938856, 2021). "HPLC assay confirms that intracellular accumulation of imatinib is accompanied by upregulation of SLC22A4 through SOS1 inhibition in both sensitive and resistant chronic myeloid leukemia cells." (PMID 34938856, 2021).
diabetes (6 papers, 2015 to 2022). "In a recent exome-chip study of genetic variants on diabetes-related metabolic traits, rs272893 was found significant that is located in SLC22A4, a gene found associated with T2D already in previous GWAS studies and closely linked to our significant SNP rs2522052." (PMID 29188820, 2018).
Sepsis (6 papers, 2021 to 2025). Sepsis is defined as life-threatening organ dysfunction caused by a dysregulated host response to infection. "Although there are no direct evidences on the relationship between G0S2, PRUNE2, SLC22A4 and septic shock or sepsis, several researches indicated their indirect association." (PMID 34772470, 2021). "Using this model, we identified five key genes for constructing the sepsis diagnostic model: SHKBP1, ICAM2, CTSD, SNX3, and SLC22A4." (PMID 41445732, 2025). "Nevertheless, other hub genes such as ICAM1, CTSD, SNX3, and SLC22A4 also demonstrated biological relevance in sepsis and may contribute to disease pathogenesis through complementary mechanisms." (PMID 41445732, 2025). "We established a diagnostic model based on five key genes(SHKBP1,ICAM2,CTSD,SNX3, and SLC22A4), and Kaplan-Meier survival analysis revealed that SHKBP1 was significantly correlated with both the diagnosis and prognosis of sepsis." (PMID 41445732, 2025).
gastrointestinal stromal tumor (5 papers, 2014 to 2024). "As examples, a high rate of loss of response to imatinib in CML was associated with the SLC22A1/OCT1 variant rs683369 (C490G) and increased time to progression of gastrointestinal stromal tumors (GISTs) on imatinib was associated with the SLC22A4/OCTN1 variant rs1050152 (C1507T)." (PMID 28350329, 2017).
ischaemic stroke (4 papers, 2020 to 2025). "Furthermore, ischemic stroke in the Japanese population was also significantly associated with the SLC22A4 gene polymorphism rs273909." (PMID 38112574, 2023). "We find these findings to be consistent with our bioinformatics analysis, suggesting that ID3, SLC22A4 and the NF-kB signaling pathway are very important for mediating biological processes involved in ischemic stroke." (PMID 38112574, 2023). "In summary, we determined that ADM, ANXA3, SLC22A4 and VIM are diagnostic markers of ischaemic stroke." (PMID 35962388, 2022). "Therefore, the regulation of SLC22A4 expression in the astrocyte may contribute to the treatment of ischemic stroke." (PMID 38112574, 2023). "The mechanism underlying the relationship between ADM, ANXA3, SLC22A4 and VIM and immune cells may be of great significance for the pathogenesis and progression of ischaemic stroke, and related research of these genes could provide new therapeutic insight for ischaemic stroke." (PMID 35962388, 2022). "Eight hub genes (ADM, ANXA3, CARD6, CPQ, SLC22A4, UBE2S, VIM and ZFP36) were revealed to be significantly correlated with ischaemic stroke by the LASSO logistic regression and SVM-RFE algorithm." (PMID 35962388, 2022). "The expression levels of the ADM, ANXA3, CARD6, CPQ, SLC22A4 and VIM genes were significantly increased in the ischaemic stroke patients compared with those in the healthy subjects (p < 0.05–0.01)." (PMID 35962388, 2022). "Third, more in vivo and in vitro studies are needed to clarify the underlying mechanism of these correlations among ADM, ANXA3, SLC22A4 and VIM and infiltrated immune cells in ischaemic stroke." (PMID 35962388, 2022). "Eight hub genes (ADM, ANXA3, CARD6, CPQ, SLC22A4, UBE2S, VIM and ZFP36) were revealed to be significantly correlated with ischaemic stroke by a LASSO logistic regression and SVM-RFE machine learning methods." (PMID 35962388, 2022). "The ROC analyses based on the training set, validation set, and our clinical samples showed that the ADM, ANXA3, SLC22A4 and VIM genes remained highly effective in distinguishing the ischaemic stroke patients from the normal subjects." (PMID 35962388, 2022). "To explore the potential side effects of these targets, we analyzed whether druggable genes influence ischemic stroke and found that TNFSF12, SLC22A4, and SPARC influence the occurrence of certain ischemic stroke subtypes." (PMID 38977622, 2025). "Further verifying the expression levels of these key genes in ischaemic stroke patients, we noticed that the expression levels of ADM, ANXA3, SLC22A4 and VIM were significantly increased in the ischaemic stroke patients compared with those in the normal subjects (p < 0.01)." (PMID 35962388, 2022). "Therefore, further studies are needed to explore whether therapies targeting these genes such as ADM, ANXA3, SLC22A4 and VIM will bring some similar risks to patients with ischaemic stroke." (PMID 35962388, 2022).
deafness (3 papers, 2013 to 2023). An inherited or acquired condition characterized by the complete loss of the ability to hear from one or both ears. "In addition, we identified potentially novel deafness-associated genes Mpzl2 in IMCs and Tbx1 in MCs along with the known deafness-associated genes in IMCs (Kcnj10, Met, Mitf, Gjb6, Ednrb, and Gjb2) and in MCs (Kcnq1, Esrrb, Kcne1, Lrp2, Slc22a4, and Hgf)." (PMID 37322474, 2023). "SLC22A4 was the most likely candidate NSHL gene, as the NM_003059.2:c.338G>A (p.C113Y) substitution within exon 1 was previously reported as a deafness-causing mutation." (PMID 33643381, 2021). "Little is known about the role of SLC22A4 in normal hearing and deafness." (PMID 33643381, 2021). "By analogy with DNFM1/METTL13, which acts as a dominant suppressor of recessive DFNB26/GAB1 deafness, it is intriguing to speculate about the existence of a dominant modifier of SLC22A4, which could suppress the onset of deafness in the non-penetrant individual from family NSHL7." (PMID 33643381, 2021).
hearing loss (3 papers, 2020 to 2022). "In the present study, we report a third ARSNHL family of Moroccan origin, carrying the same NM_003059.2:c.338G>A (p.C113Y) missense variant (rs768484124), thus providing the first independent replication of the involvement of SLC22A4 in hearing loss." (PMID 33643381, 2021). "Other members of the solute carrier family (SLC22A4, SLC26A5, SLC17A8, SLC12A2) have also been associated with non-syndromic hearing loss (hereditaryhearingloss.org)." (PMID 35741759, 2022).
type 2 diabetes (3 papers, 2006 to 2023). "Additional studies in independent populations and in both type 1 and type 2 diabetes patients will be needed to confirm the putative influence of the SLC22A4 and SLC22A5 genes in these diseases." (PMID 16796743, 2006).
Arthritis (2 papers, 2014 to 2025). Inflammation of a joint. "The affected 5q LOH interval harbors several cytokine genes (including IL-3, IL-4, IL-5, IL-13, and CSF2), a gene associated with arthritis susceptibility (SLC22A4), a DNA repair gene (RAD50), and a gene that promotes Type 1 interferon responses (IRF1)." (PMID 25107306, 2014).